GNRH1 (gonadotropin releasing hormone 1)
Diseases named in the same sentence as GNRH1 in open-access papers (continued):
Sharing a sentence is not in itself a finding about the gene and the disease.
seminoma (2 papers, 2023 to 2025). A radiosensitive malignant germ cell tumor found in the testis (especially undescended), and extragonadal sites (anterior mediastinum and pineal gland). "Among pituitary hormone genes, GNRH1 (weak effect), PRL and CGA (strong effect) were expressed at significantly higher levels in NSGCT than seminoma samples." (PMID 37669975, 2023).
teratoma (2 papers, 2022 to 2025). A non-seminomatous germ cell tumor characterized by the presence of various tissues which correspond to the different germinal layers (endoderm, mesoderm, and ectoderm). "Pituitary hormone-coding PRL and GNRH1 peaked in teratoma, while SHBG mRNA levels were the highest in yolk sac tumors." (PMID 40011822, 2025).
Arthritis (1 paper, 2024). Inflammation of a joint. "The genes with the most significantly increased expression in the synovial tissues of the arthritis-protected Mg2800 diet group included Snora34, Gnrh1, Actc1, Nr4a3, and Slc9a4." (PMID 39683640, 2024).
cervical tumors (1 paper, 2022). "We found that downregulated genes in PR patient, such as IL17D, MDK and GNRH1, which are known for their role in the innate immune system, are unfavorable prognostic factors highly expressed in primary cervical tumors and across cancers." (PMID 36171464, 2022).
cancer (304 papers, 1990 to 2026). A tumor composed of atypical neoplastic, often pleomorphic cells that invade other tissues. "The gene GNRH1 had the highest degree, and a GNRH1 related sub‐network was extracted from the global cancer hallmark insensitivity to antigrowth signals GLCRP network." (PMID 32202050, 2020). "Finally, studies have yielded mixed results regarding the association between GNRH1 and cancer." (PMID 40096084, 2025). "In fact, the newest approaches utilize GnRH1-tagged nanoparticles to directly target chemotherapeutics into cancer cells." (PMID 38260130, 2023). "For decades, we have known that GnRH1 and GnRHR1 are expressed in reproductive tumors and GnRH1 analogues inhibit cancer cell proliferation." (PMID 38260130, 2023). "A PPI network indicated the GNRH1 interacted with several important cancer-related proteins, including AKT1/3, MAPK1/3, and KISS1." (PMID 35646056, 2022). "To further explore the role of GNRH1 in cancers, we downloaded the interaction network of the top 20 proteins binding with GNRH1, which was available from the STRING website." (PMID 35646056, 2022). "It is well established that GnRH1 and its receptor are expressed in cancer cells derived from reproductive tissues and administration of GnRH1 analogs inhibits their proliferation." (PMID 29312140, 2017). "CGB and GNRH1 expression level in tumor tissue and blood of cancer patients was assessed by real-time RT-PCR." (PMID 21827674, 2011). "While the expression of both genes characterized all examined tumor tissues, in case of blood analysis, the transcripts of GNRH1 were found in all cancer patients while CGB were present in 93% of patients." (PMID 21827674, 2011). "High expression level in case of CGB and GNRH1 expression allowed identifying four and two individuals, respectively as cancer patients having tumor cell circulating in the blood flow." (PMID 21827674, 2011). "Log-transformed results of GNRH1 expression in blood of cancer patient and in tumor tissue showed remarkably similar distributions." (PMID 21827674, 2011). "The differences between CGB and GNRH1 genes expression in cancer tissue and healthy tissue was found to be statistically significant (P = 0.000000 and P = 0.001037, respectively)." (PMID 21827674, 2011). "In tumor tissue and blood of cancer patients three subpopulations with different levels of GNRH1 expression were established." (PMID 21827674, 2011). "The raw results of GNRH1 expression in blood of cancer patients was fitted to three normal distributions." (PMID 21827674, 2011). "Like GnRH1, GnRH2 analogues inhibit cancer cell proliferation; however, GnRH2 is often more potent." (PMID 38260130, 2023). "GNRH1 was also reported to be correlated with the prognosis of cancer." (PMID 35646056, 2022). "Pan-cancer analysis was conducted to explore the role of GNRH1 in tumors." (PMID 35646056, 2022). "These samples may represent tissues producing maximal level of GNRH1 or tissue fragments containing higher number of cancer cells." (PMID 21827674, 2011). "Additionally in blood of cancer patients as well as in tumor tissue a third subpopulation corresponding to extremely high activity of GNRH1 was found." (PMID 21827674, 2011). "Assessment of CGB and GNRH1 expression level in cancer patients' blood may be useful for indicating metastatic spread of tumor cells." (PMID 21827674, 2011). "The correlation between CGB and GNRH1 genes expression in different cancer types." (PMID 21827674, 2011). "However one subpopulation consists of cancer patient with much higher GNRH1 expression than in control group was found." (PMID 21827674, 2011). "Finally, we have identified mRNAs encoding proteins such as IL2RG (155%), GNRH1 (153%) and CACNA1D (130%) that are overexpressed and whose role in cancer remains unclear." (PMID 40096084, 2025). "Also, high concentrations of GnRH1 analogues are required to suppress cancer cell proliferation." (PMID 38260130, 2023).
cancer (continued). "During another study, expression of GNRH1 was considered may be a prognostic factor for metastatic spread of tumor cells based on the result that the up-regulation of GNRH1 expression suggested the presence of tumour cells in the circulation of cancer patients." (PMID 34229684, 2021). "Analysis of results demonstrated that in part of the studied blood samples of cancer patients activity of CGB and GNRH1 was on the same level as in control group." (PMID 21827674, 2011). "Finally, we have also showed the overexpression of genes whose role in cancer is not yet well understood such as IL2RG, CACNA1D and GNRH1." (PMID 40096084, 2025). "In human cancer cells with reduced GnRHR1 levels, GnRH2 (not GnRH1) retained the ability to inhibit cell proliferation." (PMID 29312140, 2017). "In some human cancer cell models GnRH II(GNRH2, O43555) is more potent than GnRH I (GNRH1, P01148), implying mediation by GnRH2 receptors, but GnRH2 receptors are not expressed by humans because the human GNRHR2 gene contains a frame shift and internal stop codon [1377]." (PMID 29055040, 2017). "The level of CGB expression in blood of cancer patients and in blood of healthy volunteers differed significantly while GNRH1 activity in the studied groups was not statistically significant." (PMID 21827674, 2011). "For GNRH1 critical value was not established since the results of the gene expression in blood of cancer patients and healthy volunteers were overlapping." (PMID 21827674, 2011). "In case of GNRH1 this value was not established since the results of the gene expression in blood of cancer patients and healthy volunteers were overlapping." (PMID 21827674, 2011). "One of the methods that is used for the engineering of targeted cancer therapy is based on the discovery that tumors produce higher levels of receptors for peptide hormones such as somatostatin, bombesin, and LHRH (now identified in genome and microarray databases as GNRH1) than most normal cells." (PMID 38167999, 2024). "CGB and GNRH1 transcripts were detected also in control tissue lacking cancerous changes, however the expression level of CGB gene in control group was significantly statistically lower than in cancer group." (PMID 21827674, 2011). "However, the remaining eight cancer-specific DESPGs of GLB1, HSPA5, PDIA3, GNRH1, IFNGR2 ADAM9, TPST2, and TAC4) were not reported in any researches, which could be potential novel prognostic biomarkers in corresponding tumors." (PMID 31824949, 2019).
tumor (218 papers, 1979 to 2026). "Given the significant discrepancy in expression levels between tumor and normal tissues in most tumor types, we next investigated the relationship between GNRH1 expression and the prognosis of different tumors." (PMID 35646056, 2022). "In particular, how GNRH1 influences tumor development in ccRCC requires further experiments in vivo and in vitro." (PMID 35646056, 2022). "An expression analysis revealed that GNRH1 was differentially expressed between tumor tissues and the corresponding normal tissues in the majority of tumor types." (PMID 35646056, 2022). "The level expression of GNRH1 has been shown to indicating metastatic spread of tumor cells in gynecological malignances." (PMID 33867351, 2021). "For example, glioblastoma-derived microvesicles increased proliferation of tumor cells in vitro; the same microvesicles were also found to carry GnRH2, GnRH1, GnRHR2, and GnRHR1 mRNA." (PMID 29312140, 2017). "CCK modifies the migratory abilities, proliferation, and survival of tumor astrocytes and lymphocytes, and guides migrating gonadotropin-releasing hormone-1 (GnRH-1) neuroendocrine neurons into the brain." (PMID 23459364, 2013). "Two of these distributions corresponding to lower level of the gene activity (mean of log10 of GNRH1 expression: 0.79 and 1.13) were similar to these observed in tumor tissue and control blood." (PMID 21827674, 2011). "Two of these distributions found in tumor blood corresponded to lower level of the gene activity (GNRH1 mean in tumor blood: 0.79 and 1.13 and in tumor tissue: 0.54 and 1.37)." (PMID 21827674, 2011). "Importantly, the anti-tumor effects of GnRH2 are often more robust than GnRH1, enhancing therapeutic potential." (PMID 38260130, 2023). "One study found that GNRH1 expression could be considered a method of tumor cell metastatic spread detection in patients with gynecological malignances." (PMID 35646056, 2022). "In addition, the GEPIA2 tool was used to evaluate the expression correlation of the hot tumor-related genes and GNRH1 in ccRCC." (PMID 35646056, 2022). "Then the mRNA expression of prognostic biomarkers between tumor tissues and normal tissues was compared, the results indicated that both the genes including GNRH1 (P < 0.05), and LTB4R (P < 0.05) were significantly higher expressed in ccRCC samples compared to normal samples." (PMID 34229684, 2021). "Thus, the expression of CGB and GNRH1 may become a prognostic factor of metastatic spread of tumor cells." (PMID 21827674, 2011). "Among them, more research has been conducted on the anti-cisplatin effect of GAST, and GNRH1 and STC1 can activate the c-Jun N-terminal kinase (JNK) pathway to facilitate tumor development." (PMID 33330624, 2020). "In case of tumor tissue CGB and GNRH1 activity were fitted into two and three normal distribution, respectively." (PMID 21827674, 2011). "On the other hand, in other 21 tumors, GNRH1 was expressed at a lower level in tumor tissues than in normal tissues." (PMID 35646056, 2022). "Moreover, the results also suggested that high expression of GNRH1 (F = 2.63, P = 0.0497) and LTB4R (F = 3.16, P = 0.0243) were significantly related to higher tumor stage." (PMID 34229684, 2021).
psychiatric disorder (3 papers, 2016 to 2022). A disorder characterized by behavioral and/or psychological abnormalities, often accompanied by physical symptoms. "Although the enrichment does not reach significance following multiple hypothesis testing comparison, it is worth noting that additional genes are implicated in psychiatric disorders (GABRE, GNRH1, FMO1, FLG, SELE, NQO2)." (PMID 33169669, 2020).
GNRH1 also shares sentences with these, for which no sentence is quoted: ovarian hyperstimulation syndrome (168 papers); polycystic ovary syndrome (116); Obesity (96); adenomyosis (86); fibroids (48); amenorrhea (43); hyperprolactinemia (42); uterine fibroids (40); hyperandrogenism (37); Anosmia (36); depression (36); Insulin resistance (35); Anxiety (27); metastatic prostate carcinoma (27); cardiovascular disease (24); myocardial infarction (23); type 2 diabetes mellitus (23); ovarian failure (21); Gonadotropin deficiency (18); Hyperinsulinemia (18); Hypertension (18); infection (18); melanoma (18); Miscarriage (18); glioma (17); metabolic syndrome (15); atherosclerosis (14); endocrine disorders (14); COVID-19 (13); cyst (13).
A further 441 diseases each share a sentence with GNRH1 in 13 papers or fewer.